GFAP (glial fibrillary acidic protein)
Diseases named in the same sentence as GFAP in open-access papers (continued):
Sharing a sentence is not in itself a finding about the gene and the disease.
varicella zoster virus (1 paper, 2017). "Similar to the results of our current study, varicella zoster virus (VZV) infection has been shown to downregulate GFAP mRNA expression in vitro." (PMID 28542613, 2017).
vascular brain injuries (1 paper, 2025). "The reason for the differences in our findings for NfL and GFAP is uncertain, but we previously demonstrated that NfL tended to be more strongly associated with vascular brain injuries than is GFAP in CHS, and the current results concord with that observation." (PMID 40596519, 2025).
Visual impairment (1 paper, 2022). "We found in patients with IIH with visual impairment significantly higher GFAP immunoreactivity (and perivascular AQP4 expression) than in those without visual impairment." (PMID 35903170, 2022).
Wilson disease (1 paper, 2021). A very rare inherited multisystemic disease presenting non-specific neurological, hepatic, psychiatric or osseo-muscular manifestations due to excessive copper deposition in the body. "This prospective cross‐observational study compared plasma glial fibrillary acidic protein concentration among different subtypes of patients with Wilson disease and healthy control subjects." (PMID 33502774, 2021). "The aim of this study was to evaluate the utility of plasma glial fibrillary acidic protein as a biomarker for neurological involvement in patients with Wilson disease." (PMID 33502774, 2021). "Plasma glial fibrillary acidic protein may serve as a biomarker for distinguishing different subtypes of Wilson disease." (PMID 33502774, 2021).
X-linked intellectual disability (1 paper, 2022). An X-linked intellectual deficiency in which not enough information is known, reported or published to indicate whether a gene causes non-syndromic or syndromic presentations.
tumor (883 papers, 1978 to 2026). "Single-cell genomics for common GBM mutations, GFAP staining, tumour specific anomalies like amplification of EGFR gene and gains and losses in chromosomes 7 and 10 genomic regions by chromosomal and array CGH on whole genome amplification." (PMID 40867329, 2025). "The correlation between GFAP and overall survival remained consistent with the loss of GFAP in high-grade tumors and the subsequent increase in tumor growth." (PMID 39821858, 2025). "GFAP+ or Vimentin+ SCs were closely associated with cancer cells by infiltrating in tumour stroma (higher magnification images)." (PMID 37830980, 2023). "GFAP is associated with various neurological disorders such as brain injury, inflammation, and neurodegenerative diseases, or as a marker of neoplasms originating from glial cells in the CNS." (PMID 37760333, 2023). "Loss of GFAP in astrocytoma has been associated with high-grade tumors and cellular loss is associated with faster tumor growth." (PMID 35073955, 2022). "The tumor cells typically show a loss of GFAP expression, but express neuronal markers such as synaptophysin or NSE." (PMID 36414742, 2022). "The diagnosis in patients in which a tumor is found after detecting GFAP antibodies should depend upon clinical symptoms and imaging findings; if these are caused by a tumor space-occupying effect, we propose that “tumor only” should be the diagnosis." (PMID 34880859, 2021). "Even the very strong GFAP expression in the tumor of classic olidendroglial-like histology was associated with the abundant reactive component of stromal astroglia." (PMID 32650833, 2020). "GFAP is also associated with a more aggressive tumor growth and it was mentioned as a characteristic of the mesenchymal subtype before." (PMID 33066251, 2020). "Surprisingly, our findings ruled out a role for classical anti-tumor effector cells such as CD8+ T cells and NK cells, as mice depleted of either of these subsets still exhibited dramatic reductions in tumor burden following the loss of the GFAP+ glia." (PMID 33282743, 2020). "What’s more, two same gene mutations of KMT2A and TMPRSS2 were checked out in GFAP separated CTCs and tumor tissue." (PMID 33208163, 2020). "FK506 is capable of reversing this mechanism, as the treatment of FK506 in combination with Vc showed, reducing tumor volume as well as reducing GFAP, nestin, and Ki67 levels, which are associated with GBM aggressiveness." (PMID 30208561, 2018). "P5 regrowing tumor revealed almost complete loss of GFAP, diffuse nestin staining, and de novo focal EMA reactivity in a dot-like pattern, compared to the primary one." (PMID 29805974, 2018). "First, although transposase expression was detected in a subset of GFAP+ cells in these mice, it is possible that the rate of mutagenesis or the number of cells undergoing mutagenesis was too low to cause overt tumor formation." (PMID 25423036, 2014). "Collagen I depositions were observed in three separate areas: intimately associated with high Endo180 expressing, GFAP-positive tumor cells, in GFAP-negative stromal regions, and, to a lesser extent, adjacent to vascular proliferations." (PMID 20339555, 2010). "Notably, Prickle4 expression did not colocalize with CD31, but was instead associated with the tumor marker GFAP (Pearson's correlation analyses)." (PMID 41236163, 2026). "In this study, we explored the effect of a CRC environment on enteric glia and investigated the distribution of the immunohistochemical marker GFAP in the tumor and its association with clinicopathological characteristics in a large population-based CRC cohort." (PMID 40580485, 2025). "This indicated that GFAP-positive cells might be associated with tumor localization and median survival." (PMID 40580485, 2025). "Damage Biomarkers: A hypothesis to be tested is whether exceptionally high initial levels of serum GFAP or NfL might correlate with a more aggressive underlying tumor driving a more violent initial autoimmune attack." (PMID 40963604, 2025).
tumor (continued). "Such plasticity could underlie the GFAP expression observed in this work and potentially influence tumor behavior and progression." (PMID 40805120, 2025). "Therefore, patients should be monitored for underlying neoplasms within 2 years of GFAP disease onset." (PMID 35065659, 2022). "However, the internal part of the tumor showed areas with a more aggressive appearance, with anaplastic GFAP positive cells with cellular polymorphism." (PMID 35725578, 2022). "The histology showed a tumor with fibrillary background and increased cellularity, with pleomorphic cells but without microvascular proliferation or necrosis; the immunohistochemical study was positive for GFAP and IDH1 R132H mutation." (PMID 35884525, 2022). "However, the causality between auricular tumor formation and GFAP-Cre mediated Pcdh10 ablation was further strengthened in the following ways: i." (PMID 35468745, 2022). "Second, the tumour may be causing peripheral brain damage resulting in GFAP release and damage to the BBB." (PMID 35919979, 2022). "Additionally, co-staining of sequential sections for GFAP or S-100 confirmed the distinction between tumor and underlying normal brain tissue." (PMID 32967361, 2020). "Furthermore, gene mutation detection in separated CTCs by GFAP-IMLs also indicated the tumor-derived circulating cells." (PMID 33208163, 2020). "Loss of GFAP expression in tumor progression could be secondary loss of a differentiation marker and represented a step in tumor development." (PMID 23601182, 2013). "Hence, the observed anti-GBM action by BA could be attributed, to a greater or lesser extent, to its tumor-suppressing potency associated with GFAP, Ki67, Nop10, and H2AX expressions." (PMID 39821858, 2025). "However, for tumours with early onset of characteristics associated with poor prognosis (necrosis and vasculature damage), serum GFAP may be used for earlier detection." (PMID 35919979, 2022). "Thus, patients should be monitored for underlying neoplasms within 2 years of GFAP disease onset." (PMID 33569363, 2020). "Furthermore, Phα1β caused significant reduction of tumor areas in vivo and this toxin also increased GFAP-activated astrocytes and Iba-1 positive microglia in the peritumoral region, showing a modulation of these immune cells, which corroborates current findings." (PMID 32246025, 2020). "The results showed that the majority of APOE spots were found within GFAP + astrocytes at the tumor edge in the ALTS1C1 model (72.5 ± 10.7%)." (PMID 40745073, 2026). "For example, GFAP which is considered as a prototype glial-specific biomarker, lacks tumor specificity." (PMID 41399659, 2026). "Immunohistochemical analysis revealedextensive coagulative and glial necrosis, elevated GFAP expression,and a reduced Ki67 index, consistent with effective tumor ablation." (PMID 41493881, 2026). "Tumor cells were immunopositive for glial fibrillary acidic protein (GFAP), epithelial membrane antigen (EMA) in a dot-like pattern, and D2-40." (PMID 42164214, 2026). "Immunohistochemically, tumor cells showed strong and diffuse cytoplasmic positivity for vimentin, while glial fibrillary acidic protein (GFAP) expression was sparse and showed scattered cytoplasmic positivity in neoplastic cells." (PMID 42038044, 2026). "Earlier studies in our lab have also found a correlation between carbonic anhydrase IX (CAIX) expression and GFAP + astrocytes at the tumor edge, indicating the alteration in astrocyte metabolism during glioma invasion." (PMID 40745073, 2026). "Immunohistochemically, the tumor cells were positive for S-100 protein, glial fibrillary acidic protein (GFAP), and epithelial membrane antigen (EMA) with dot-like positivity, and negative for oligodendrocyte transcription factor 2 (Olig2)." (PMID 40896082, 2025).
tumor (continued). "After 48 h, IF revealed an increased number of tumor cells and GFAP-positive astrocytes and decreased TEER in the shRBM10 group." (PMID 40069781, 2025). "We therefore propose that GBM recruits a large number of GFAP-positive astrocytes to the peritumoral region during tumor progression and induces them to express CAF-related proteins." (PMID 40530702, 2025). "In this study, we examined how certain proteins—neuropilin-1 and glial fibrillary acidic protein (GFAP)—are distributed in tumor tissue and how they relate to blood vessels, immune cells, and tumor behavior." (PMID 40805120, 2025). "To investigate the involvement of NRP1 at the BBB, we compared endothelial NRP1 staining with the presence of astrocytic end feet (GFAP+) surrounding or in close contact with tumor vessels." (PMID 40805120, 2025). "Glial fibrillary acidic protein (GFAP)+/S100β+ astrocytes secrete PA, which induces tumor cell apoptosis and limits the activation of L1CAM to restrict tumor dissemination." (PMID 41429896, 2025). "Immunohistochemical staining can further confirm the glial origin of the tumor, often through markers like glial fibrillary acidic protein (GFAP)." (PMID 39796773, 2025). "Co-localization of EphB4/ephrin-B2 with CD34 in stromal microvessels and GFAP in tumor cells has been observed, with higher expression levels in poorly differentiated tumors, reinforcing its relevance to both tumor aggressiveness and vascular pathology." (PMID 41200151, 2025). "Immunohistochemistry detected various extents of genuine glial fibrillary acidic protein (GFAP) expression by the tumor cells." (PMID 40237561, 2025). "Through the fusion, the GFP+/c-MYChigh cells of the tumor sphere encountered contact to astrocytic cells (GFAP+) and neurons (MAP2+) from the outer edge of the organoid." (PMID 40917877, 2025). "Functional experiments confirm that lactate in the hypoxic tumor microenvironment can induce GFAP-dedifferentiation in SCs, which promotes cancer cell invasion and progression through upregulating HMGB1." (PMID 40148311, 2025). "This enables direct examination of spatial distribution patterns for key markers such as Ki67, GFAP, and NeuN from transcriptomic data, transforming tumor classification and microenvironmental interaction analysis." (PMID 40940870, 2025). "Based on our preliminary findings, after the application of PDT, the number of TUT+ cells (corresponding to neurons) remained unchanged, while the GFAP+ cells (considered as reactive astrocytes) diminished in the area surrounding the tumor." (PMID 41009470, 2025). "Immunohistochemical markers commonly observed in intraventricular DMG tumor case reports, were GFAP, Olig2, Ki67, and S100, were also expressed." (PMID 40182052, 2025). "Glial fibrillary acidic protein (GFAP) is observed in the glial component of the tumours and synaptophysin is seen in the neuronal or ganglion cell components." (PMID 40013208, 2025). "They found that tumour growth increased microglial Iba and astrocytic GFAP expression in the amygdala and hippocampal brain regions." (PMID 40172096, 2025). "Futhermore, the number of glial fibrillary acidic protein (GFAP)–positive astrocytes, a marker of brain metastasis, also increased, suggesting mutual stimulation between tumor cells and astrocytes." (PMID 40069781, 2025). "In both groups, C5b-9 was predominantly detected on tumor-specific circulating sEVs (glial fibrillary acidic protein (GFAP)-positive sEVs) with high VEGF-A expression, while C5b-9 was significantly less frequent on sEVs with low VEGF-A expression (p < 0.05)." (PMID 39996852, 2025). "Pathologically, tumor cells are perivascular pseudorosettes, presenting immunoreactivity for GFAP, S-100, Vimentin, “dot-like” staining for EMA, and low proliferative activity." (PMID 39098857, 2025). "The protrusions of astrocytic cells (GFAP+) were observed to spread from the interaction site into the tumor sphere, while this was observed less extensively for the neurons (MAP2+)." (PMID 40917877, 2025).
tumor (continued). "In SHH-MBs, a subset of tumor cells showed aberrant GFAP expression, which correlated with tumor recurrence or progression." (PMID 40805120, 2025). "In cells transduced with AAV8-GFP, GFP did not colocalize with astrocytes expressing glial fibrillary acidic protein (GFAP) or microglia positive for ionized calcium-binding adaptor molecule 1 (IBA1) at the tumor border." (PMID 39563028, 2025). "In accordance with the NLRP3 expression variation, the GFAP + PTX scaffold promoted a significant increase in the caspase-1 expression in tumor cells compared with the GF + PTX scaffold (p < 0.05), strengthening the results obtained previously." (PMID 39940603, 2025). "In the low-cellularity areas, all tumor types demonstrated a uniformly strong GFAP fibrillary background." (PMID 41464145, 2025). "Immunohistochemical staining revealed that GFP+ tumor cells in both control and Olig1/2F/+; H2bF/+ groups exhibited robust expression of astrocytic markers, including GFAP and SOX9." (PMID 40428395, 2025). "Albeit generally low across both tumor entities, the density of GFAP-positive astrocytes was significantly higher within U87COX−2KO tumors." (PMID 40649978, 2025). "Glial fibrillary acidic protein (GFAP) staining indicates higher astrocyte activation at tumor margins in control sections, while treated tumors show reduced glial reactivity." (PMID 40249282, 2025). "The possibility of Myenteric plexus origin of the tumor was indicated by positive immunoreactivity for glial fibrillary acidic protein (GFAP)." (PMID 40743688, 2025). "In the group receiving the peritumoral implantation of GFAP, inflammatory infiltrates appeared within the tumors by the second week, accompanied by tumor cells exhibiting condensed, pyknotic nuclei." (PMID 39940603, 2025). "Immunohistochemically, the tumor cells were positive for GFAP and S‐100 protein, weakly positive for SOX2, focally positive for synaptophysin, and negative for TTF‐1, neurofilament protein, NeuN, EMA, chromogranin, and BCOR." (PMID 39492623, 2025). "Again, B3 revealed mild cytoplasmic Ki67 and CMPK2 expressions in tumor cells around blood vessels, along with moderate GFAP expression in astrocytes surrounding the tumor." (PMID 39821858, 2025). "Alterations in enteric glial function and changes in glial GFAP expression are correlated with tumor presence and severity in the gastrointestinal tract." (PMID 39546562, 2025). "Typical histological features of the tumor include pleomorphic, lipid-containing cells, expressing GFAP and often surrounding reticular fibers and eosinophilic granulocytes, but lacking fibroproliferative features." (PMID 39995830, 2025). "In accordance with these findings, we observed mild GFAP expressions in astrocytes surrounding the tumor mass." (PMID 39821858, 2025). "Researchers focussed on Frizzled 9, GFAP, CD133, Vimentin, and SSEA4, which are associated with stem cell self-renewal, differentiation, and tumour initiation." (PMID 39316249, 2025). "GFAP expression was observed in a subset of cases, supporting the myoepithelial nature of the tumor." (PMID 41440486, 2025). "Compared with wild-type controls, tumor organoids presented increased βIII-Tubulin+ neural density after 7 days, accompanied by glial fibrillary acidic protein (GFAP)+ glial cell recruitment, reflecting early neuro-glial activation." (PMID 40243726, 2025). "The selection of ROIs was guided by immunofluorescence-based morphology marker staining for SOX2, IBA1, and GFAP, and ROIs were chosen based on the highest tumor cell density." (PMID 40960500, 2025). "The analysis of Olig1/2F/+; ISF/+ tumor-bearing mice at P40 demonstrated significantly reduced tumor sizes compared to controls, while tumor cells maintained high expression of astrocytic markers GFAP and HOPX." (PMID 40428395, 2025). "Concurrently, GFAP, although a canonical glial marker, facilitates tumor cell migration and invasion by remodeling the cytoskeleton in certain neoplastic contexts." (PMID 41281378, 2025).